TNF (tumor necrosis factor)
Diseases named in the same sentence as TNF in open-access papers (continued):
Sharing a sentence is not in itself a finding about the gene and the disease.
pancreatitis (continued). "Besides the observation that CCL5 is produced by PDAC cells in the same manner as CCL2, a recent report elegantly showed that the secretion of RANTES and TNF-α through macrophages secrete RANTES/CCL5 and TNF-α in pancreatitis induced acinar-to-ductal metaplasia (ADM)." (PMID 31561620, 2019). "IL-17A delivery in these strains revealed thatneither IL-6 nor signalling via these TNF or IL-1 receptors were required forthe development of pancreatitis: all mice tested developed neutrophil aggregatesand pancreatitis in response to IL-17A in a similar manner." (PMID 26964500, 2016). "Indeed, we observed that induction of pancreatitis robustly increased plasma concentration of several inflammatory cytokines including IL1α (2.6-fold), IL1β (12.8-fold), VEGF (70.5-fold) TNFα (4.5-fold), and IL6 (585.2-fold) as well as stimulated p38 kinase activation in pancreatic tissue." (PMID 24480543, 2014). "In the patients without post-ERCP pancreatitis, a positive correlationwas found between IL-4 and TNFα levels at 24 hours after ERCP (r = 0.397; P = .018),but there was a negative correlation between IL-4 and IL-6 levels at 12 hoursafter ERCP (r = 0.392; P = .018)." (PMID 18670651, 2008). "The levels of IL-4 at 24 hours after ERCP were significantly lower in the patients with post-ERCP pancreatitis than in those without pancreatitis, while TNFα levels at 12 hours after ERCP were higher in the complicated group than those of the uncomplicated group." (PMID 18670651, 2008). "Therefore, we surmise that the TNF and TGFB1 genes are upregulated by TMAO and that the TGFB gene participates in regulating the expression and activation of TNF, which increases the expression of the inflammatory factor TNF-α and induces a sensitive state of pancreatitis." (PMID 34925503, 2021). "In our study, a group of patients continued taking budesonide and anti-TNF even after cessation of AZA; however, no additional pancreatitis occurred thereafter in either the AZA-AP or control groups." (PMID 41375842, 2025). "Vitamin D acts as a negative modulator of TNF-α and IL-6 release, decreasing TNF-α, IL-6, and C-reactive protein (CRP) levels in pancreatitis." (PMID 35631254, 2022). "The ratios of TNFα/IL-4 at 12 and 24 hours after ERCP were found significantly higher in the patients with post-ERCP pancreatitis than in those without pancreatitis." (PMID 18670651, 2008). "On admission, mean plasma levels of neither IL-8 nor TNF-α and CRP showed any significant difference between two groups but on day 2, significantly higher values for IL-8 were observed on the group of patients with severe pancreatitis." (PMID 20130823, 2009).
malnutrition (158 papers, 2002 to 2026). Inadequate nutrition resulting from poor diet, malabsorption, or abnormal nutrient distribution. "Prospective observational clinical trials are needed to investigate associations between inflammatory parameters (e.g., TNF alpha and interleukins) and malnutrition." (PMID 41514593, 2025). "It has been shown that inflammatory factor expression is significantly upregulated in hypertensive patients, such as IL-6 and TNF-α, and malnutrition is associated with the activation of inflammatory factors." (PMID 37465450, 2023). "Vitamin D modulates pro-inflammatory cytokines that are associated with malnutrition, i.e., IL-1, Il-7, TNF-α." (PMID 36983369, 2023). "Despite these limitations, TNF-α -1,031 T/C gene polymorphism is still a potential predictor of GC malnutrition." (PMID 37533569, 2023). "The association of TNF-α-1031T/C SNP with malnutrition or inflammation has also been partially investigated." (PMID 37533569, 2023). "In cancer and cancer-related malnutrition, high production of cytokines such as TNF-α, IL (interleukin) -2, and IL-6 cause metabolic disruption which inhibits albumin gene expression and causes vascular permeability." (PMID 36869395, 2023). "According to GLIM, independent predictors of higher risk of malnutrition include CC (p = 0.013; OR = 20.114) and CT (p = 0.002; OR = 3.218) genotype of the TNF-α gene." (PMID 37533569, 2023). "Several polymorphisms of TNF-α have also been described in the available literature as detrimental factors contributing to malnutrition." (PMID 37533569, 2023). "The TNF-α 308 G/A polymorphisms is one of the most frequently related with risk of malnutrition and tumor aggressiveness." (PMID 34900737, 2021). "This study, in consonance with earlier research, shows that systemic inflammation marked by elevated IL-6, CRP, and TNF-α levels is associated with functional decline and malnutrition, two central components of the frailty syndrome." (PMID 33166358, 2020). "Malnutrition is associated with increased level of tumor necrosis factor-α (TNF-α) in patients undergoing dialysis." (PMID 32509039, 2020). "These patients were at a higher risk of malnutrition due to cancer-induced metabolism, lower dietary intake and the effect of tumor necrosis factor-alpha on alteration of liver protein production." (PMID 32664910, 2020). "Some of these factors are well-known causes of systemic immunosuppression, such as HIV, malnutrition, and anti-tumor necrosis factor (TNF) therapy." (PMID 30619306, 2018). "Inflammation has been associated to malnutrition, and consistent with this association, our results show increased levels of TNF-α in the plasma." (PMID 27548305, 2016). "The decrease in TNFα expression aligns with the notion that these supplements might contribute to decreasing the chronic inflammatory state associated with malnutrition and renal dysfunction." (PMID 38256206, 2024). "Under normal conditions, TNF-α has protective effects against tumors and infections, but persistent high expression or dysregulation of its relationship with other cytokines can cause fever, shock, and malnutrition in the body." (PMID 37533569, 2023). "The most recent of these studies demonstrated that the TNF-α-1031T/C SNP (rs1799964) may be associated with malnutrition." (PMID 37533569, 2023). "Consistent with the association between inflammation and malnutrition, evidence has been provided concerning an inverse correlation between BMI in malnourished, healthy individuals and increased plasma levels of tumor necrosis factor α (TNF-α)." (PMID 36615766, 2022). "In animal models, malnutrition has been linked to reduced lymphocyte counts, as well as decreased expression of tumor necrosis factor (TNF), interferon-gamma (IFNγ), and nitric oxide synthase (NOS)-2 which are essential for generation of mycobactericidal nitrogen oxide." (PMID 30917170, 2019).
malnutrition (continued). "The increased TNFα secretion may induce a hypermetabolic status that may be a cause of malnutrition and cancer cachexia." (PMID 11986770, 2002). "It has been shown that an increase in RDW is triggered by nutritional deficiency caused by iron, vitamin B12, and folic acid deficiency and is associated with chronic inflammation and acute phase inflammation markers, such as C-reactive protein, tumor necrosis factor (TNF), and interleukin-6." (PMID 37404429, 2023). "In addition, TNF-α is produced by cancer cells and could be one of the main factors causing muscle (especially skeletal muscle) wasting in malnutrition." (PMID 35884467, 2022). "Pro-inflammatory cytokines, including IL-6, IL-1β, and TNF-α, are released, activating pathways contributing to malnutrition development." (PMID 40507748, 2025). "Future investigations should establish longitudinal monitoring frameworks integrating CRP, IL-6, and TNF-α to disrupt the “inflammation-malnutrition” vicious cycle and improve long-term outcomes." (PMID 40630494, 2025). "Inflammatory markers such as CRP and TNF-α can suppress appetite, impairing protein and fat metabolism, which ultimately leads to malnutrition." (PMID 40655484, 2025). "Group B, which received the combined therapy, showed better results compared to group A, with reduced malnutrition grades and lower levels of inflammatory markers such as TNF-α, CRP, and IL-6 after treatment." (PMID 41281287, 2025). "Malnutrition activates the nuclear factor kappa-B (NF-κB) pathway, promoting the release of proinflammatory cytokines such as tumor necrosis factor-alpha (TNF-α) and interleukin-6 (IL-6), which induce myocardial fibrosis and microvascular dysfunction." (PMID 41189988, 2025). "On the other hand, TB leads to malnutrition by triggering the release of pro-inflammatory cytokines such as TNF-α (tumor necrosis factor-alpha), IL-6, and IFN-γ, which increase basal metabolic rate, leading to excessive energy consumption." (PMID 40549763, 2025). "Inflammatory markers such as C-reactive protein (CRP), interleukins (e.g., IL-6), and tumor necrosis factor-alpha (TNF-α) are commonly used to assess malnutrition in the elderly." (PMID 39125381, 2024). "Malnutrition can induce a low-grade systemic inflammatory response with elevated serum levels of TNF, IL-1β, and IL-6." (PMID 38651412, 2024). "Previous studies have demonstrated a strong association between circulating inflammatory markers, such as CRP, IL-6, IL-10, and TNF-α, and malnutrition." (PMID 38474705, 2024). "TNF-α also can penetrate the blood–brain barrier, leading to anorexia and further aggravating malnutrition in patients." (PMID 38751736, 2024). "The release of proinflammatory cytokines, such as IL-6, IL-1β, and TNF-α, is determinant of the pathophysiology of malnutrition." (PMID 39683535, 2024). "Pro-inflammatory cytokines including interleukin 6 (IL-6), interleukin 1β (IL-1β) and tumor necrosis factor α (TNF-α) are released, triggering several mechanisms which contribute to the pathogenesis of malnutrition." (PMID 36904164, 2023). "Conversely, increased levels of CRP and its end products, tumor necrosis factor-alpha (TNF-α) and interleukin-6 (IL-6), lead to decreased levels of the malnutrition marker albumin." (PMID 37760482, 2023). "In CD patients, the severity of malnutrition is largely dependent on the activity, duration and extent of bowel inflammation, which is regulated by proinflammatory cytokines, particularly TNF-α." (PMID 36824176, 2023). "Anti-TNF therapy tended to reduce the malnutrition probability as assessed by Cox regression analysis (OR: 0.217, 95% CI 0.057–0.821, p = 0.024)." (PMID 36824176, 2023). "In a multivariate analysis by the Cox regression model, patients with anti-TNF therapy showed a higher malnutrition-free probability according to the MNA (p = 0.024)." (PMID 36824176, 2023).
malnutrition (continued). "In 71 patients with anti-TNF therapy, 15 (21.13%) scored ≥3 as assessed by NRS2002, suggesting a high risk of malnutrition and the need for nutritional support." (PMID 36824176, 2023). "First, tumor necrosis factor-alpha (TNF-α), a key inflammatory mediator, was found to be higher in patients with moderate-to-severe malnutrition." (PMID 35284455, 2022). "Tumor necrosis factor α is a proinflammatory cytokine that plays a pivotal role in the development of malnutrition and cachexia in cancer patients." (PMID 35884467, 2022). "Tumor necrosis factor α (TNF-α) is a proinflammatory cytokine that plays a pivotal role in the development of malnutrition and cachexia in cancer patients." (PMID 35884467, 2022). "Factors that negatively affect linear growth are increased levels of inflammatory cytokines such as interleukin-6 (IL-6) and tumor necrosis factor-α (TNF-α), malnutrition, suppression of serum IGF-1 levels, and disease severity." (PMID 33446154, 2021). "WAT contains large lipid droplets and releases adipokines (FFAs, TNF-α, IL-6, IL-10, resistin, leptin, and adiponectin) to maintain metabolic homeostasis and stores TG for future energy production during periods of malnutrition." (PMID 33947969, 2021). "Malnutrition has been shown to interact with many important wound healing pathways, including upregulation of IL-6 and TNF-a, as well as inhibiting collagen synthesis." (PMID 33850181, 2021). "Previous studies have demonstrated a relationship between malnutrition and elevated levels of IL-6 and TNFα." (PMID 32297262, 2020). "We also investigated the association between serum inflammatory markers (IL-6, IL-8, TNF-α, and CRP) and overall functional decline (ADL and TUG) and malnutrition." (PMID 33166358, 2020). "Some studies have reported an association between increased levels of inflammation biomarkers such as TNF-α, malnutrition status, and poor outcome in patients with HF." (PMID 30678180, 2019). "Low calorie intake, due to appetite loss and suppression of hypothalamus by some hormones and cytokines such as cholecystokinin and tumor necrosis factor-alpha (TNF-alpha), is one of the most common causes of malnutrition in cirrhotic patients." (PMID 30949315, 2019). "Conversely, THI patients with low levels of cytokines had lower risk of malnutrition during their stay in the ICU, IL-10 and TNFα (p < 0.001 to 0.01), IL-6 and IL-1β (p 0.23 to 0.900)." (PMID 31443251, 2019). "We also studied a model of malnutrition model of skeletal muscle cell by TNF-α in C2C12 cells to determine if the effects of BYJD decoction were due to a direct effect on muscle cells." (PMID 28286533, 2017). "The adverse factors for malnutrition include disordered hormones, inflammatory cytokines (e.g., IL-6, TNFα, CRP), cigarette smoking, poor physical activity, and hypoxemia." (PMID 27669818, 2016). "In a study enrolled with eighty children aged one to five years with moderate and severe malnutrition showed increased TNF-α and IL-10 serum levels." (PMID 25095704, 2014). "Independent effects of inflammatory states on malnutrition: inflammatory cytokines such as TNF-α and interleukin-6 are elevated in hemodialysis patients, and these factors exacerbate malnutrition by promoting proteolysis, inhibiting protein synthesis, and affecting energy metabolism." (PMID 39993135, 2025). "Previous studies have indicated that cancer can trigger the release of proinflammatory cytokines such as TNF-alpha, IL-6, and IL-1, leading to malnutrition through various processes such as CNS-driven anorexia, muscle wasting, changes in liver metabolism, and fat utilization and depletion." (PMID 40384994, 2025). "Moreover, malnutrition impairs glutathione synthesis and augments oxidative stress, amplifying TNF-α-induced genotoxicity." (PMID 41473193, 2025). "Moreover, low albumin levels and malnutrition affect the adverse effects of anti-TNF administration, as does corticosteroid use." (PMID 41155581, 2025).
malnutrition (continued). "While CRP was associated with various nutritional parameters such as reduced dietary intake and weight loss, neither IL- 6 nor TNF-α showed a significant association with malnutrition risk parameters according to the NRS total score or its components." (PMID 40275239, 2025). "Importantly, TNF-α and malnutrition are biologically intertwined: TNF-α suppresses appetite, augments muscle catabolism, and disrupts intestinal tight-junctions, thereby perpetuating nutrient loss and further fuelling inflammation." (PMID 41473193, 2025). "In addition, inflammatory factors such as IL-6 and TNF-α can promote muscle proteolysis, inhibit appetite, and then lead to malnutrition." (PMID 40630494, 2025). "Low albumin levels were related to poor outcomes in patients with malignant diseases, reflecting both malnutrition and inflammation; it is worth noting that pro-inflammatory cytokines like interleukin 6 (IL-6) and tumour necrosis factor alpha (TNF-α) decrease albumin synthesis." (PMID 41228489, 2025). "The risk of strongyloidiasis is significantly increased in patients with immunosuppressive factors, such as hypochlorhydria, leprosy, long-term corticosteroid use, HIV and HTLV-1 infections, anti-tumor necrosis factor α therapy, organ or bone marrow transplantation, and malnutrition." (PMID 40776929, 2025). "In addition, Tumor necrosis factor- α (TNF α), interleukin (IL)-1, and IL-6 are examples of inflammatory mediators that are released during malnutrition associated with cancer and can control hunger and the body’s absorption of nutrients." (PMID 39434876, 2024). "A hemolytic crisis can serve as the origin of a pro-inflammatory cascade encompassing tumor necrosis factor-α (TNF-α), interferon-α, and other cytokines, which, in conjunction with oxidative stress due to malnutrition, might elicit hypertriglyceridemia." (PMID 39328659, 2024). "TNF-α is probably the most characteristic cytokine in malnutrition." (PMID 37533569, 2023). "Early application of anti-TNF therapy significantly affected skeletal muscle mass, fat mass and bone mineral content, supporting their long-term nutritional status and reducing their probability of malnutrition." (PMID 36824176, 2023). "Consequently, we supposed that earlier anti-TNF therapy was effective in reducing the potential for malnutrition." (PMID 36824176, 2023). "High levels of inflammatory cytokines, such as tumor necrosis factor α (TNF-α), interleukin (IL) 1β, IL-6, and CRP, together with loss of muscle mass, could account for malnutrition in affected patients." (PMID 37630691, 2023). "The decrease in BMD caused by malnutrition may be due to systemic inflammatory responses in COPD patients, such as tumor necrosis factor (TNF)-α." (PMID 37240965, 2023). "Early application of anti-TNF therapy significantly affected the skeletal muscle mass, fat mass and bone mineral content, supporting their long-term nutritional status and reducing the probability of malnutrition in these patients." (PMID 36824176, 2023). "In addition, the malnutrition status of the study cohort coincided with high levels of inflammatory mediators such as tumor necrosis factor-alpha and hs-CRP, which are highly correlated with the risk of CVD and heart arrest." (PMID 37964931, 2023). "The decrease in BMD caused by malnutrition may be due to systemic inflammatory responses in COPD patients, such as TNF‐α, a proinflammatory cytokine, which causes malnutrition in COPD." (PMID 35688435, 2022). "We performed a series of multivariate linear regression analyses to evaluate whether there was any relationship between AGEs, RAGEs, and their ratio with inflammatory markers that were mainly associated with malnutrition (i.e., CRP and TNFα)." (PMID 35883745, 2022).